LMNB1 (lamin B1)
Diseases named in the same sentence as LMNB1 in open-access papers (continued):
Sharing a sentence is not in itself a finding about the gene and the disease.
aneurysm (1 paper, 2025). Bulging or ballooning in an area of an artery secondary to arterial wall weakening. "Both telomere quantification and Lamin B1 expression showed accelerated molecular aging in aneurysm tissue." (PMID 41026146, 2025). "Oxidative stress reduced the length of telomeres, lowered the aging marker Lamin B1, and increased P21 expression in vitro endothelial cell models, similar to human aneurysm tissue." (PMID 41026146, 2025). "The immunofluorescence staining seemed to show enhanced Lamin B1 expression in aneurysm tissue compared to the control vessel." (PMID 41026146, 2025).
Anxiety (1 paper, 2024). Intense feelings of nervousness, tension, or panic often arise in response to interpersonal stresses. "The suspected upregulation (reduced DNAm at TSS) of LMNB1 in relation to increased separation anxiety symptom scores presents a challenge to extrapolating meaning." (PMID 38577817, 2024). "Sobel test indicated that the association between mother abused by her father in childhood and male offspring separation anxiety symptom score was mediated by DNAm of cg18262958 (LMNB1) at birth (z-score = −2.018, p = .043)." (PMID 38577817, 2024).
astrocytoma (1 paper, 2021). "In TCGA database, we found that LMNB1 and DLGAP5 were highly expressed in oligodendrogliomas, astrocytoma and GBM." (PMID 33956061, 2021).
brain tumors (1 paper, 2022). "Western blots were used to confirm the presence of LMNB1 in the total fraction of CSF from the EVD of the control and brain tumor patients." (PMID 36005596, 2022). "ELISA was used to validate the proteomic results regarding LMNB1 expression in the total fraction of CSF from the EVD of the control, MB, and other brain tumors." (PMID 36005596, 2022).
chronic cervicitis (1 paper, 2024). Chronic inflammation of the cervix. "We found that the expression of Lamin B1 was significantly lower in precancerous samples relative to noncancerous (chronic cervicitis) samples." (PMID 39727946, 2024). "We used a set of patient-derived precancerous (n = 32) and noncancerous (chronic cervicitis; n = 10) tissue samples to investigate the gene expression of several OIS (LMNB1, CDKN2A, CDKN2B, and CDKN1A), and SASP (IL1A, CCL2, TGFB1, CXCL8, and MMP9) biomarkers using qRT-PCR." (PMID 39727946, 2024).
chronic lymphocytic leukaemia (1 paper, 2018). "Finally, Lamin B1 expression level correlated with progression-free and overall survival in chronic lymphocytic leukaemia, and was strongly involved in the transformation of follicular lymphoma." (PMID 28804121, 2018).
chronic myelogenous leukemia (1 paper, 2016). "Here, we selected to examine the distribution of specific chromatin domains identified as interacting with Lamin B1 in 118 clones of the haploid chronic myelogenous leukemia cell line KBM-7 as a surrogate for human neutrophils." (PMID 27703927, 2016).
cognitive decline (1 paper, 2019). "Loss of lamin B1 has been associated with cognitive decline and neurodegenerative pathology." (PMID 31727161, 2019).
Cognitive impairment (1 paper, 2021). Abnormal cognition is characterized by deficits in thinking, reasoning, or remembering. "Given the increase in lamin B1 levels and the altered nuclear morphology and function found in R6/1 mice brain neurons, we hypothesized that these disturbances could be possibly contributing to motor and cognitive impairment present in HD." (PMID 33369245, 2021).
colorectal adenocarcinoma (1 paper, 2024). The most common type of colorectal carcinoma. "The results of early studies showed that LMNB1 expression was downregulated in colorectal adenocarcinoma cells." (PMID 38824174, 2024).
dysferlinopathy (1 paper, 2024). "Our proteomic analyses unveiled a notable elevation in the levels of Lamin A/C and Lamin B1 in dysferlinopathy." (PMID 39350328, 2024).
endometrial cancer (1 paper, 2022). Primary or metastatic malignant neoplasm involving the endometrium (mucous membrane that lines the endometrial cavity). "Further, we analyzed the enriched RNAs in apoptosis pathways, and the CPTAC database showed that their encoded proteins were upregulated in endometrial cancer tissues, including ITPR3, LMNB1, PARP1, PARP4, and TUBA1C." (PMID 36566215, 2022). "Then we analyzed the RNAs enriched in the apoptotic pathway through CPTAC database, and showed that the protein level of ITPR3, LMNB1, PARP1, PARP4, and TUBA1C were upregulated in endometrial cancer tissues." (PMID 36566215, 2022).
esophageal carcinoma (1 paper, 2021). A primary or metastatic malignant neoplasm involving the esophagus. "Its noteworthy that loss of Lamin B1 expression was identified in different malignant tissue such as prostate, breast and esophageal carcinoma, indicating that the decline of Lamin B1 expression might be considered a malignancy biomarker." (PMID 33948615, 2021).
Ewing sarcoma (1 paper, 2024). A small round cell tumor that lacks morphologic, immunohistochemical, and electron microscopic evidence of neuroectodermal differentiation. "In summary, our findings demonstrate the EWS::FLI1/P300/CBP axis directly regulates the expression of key senescence-related genes LMNB1, promoting cell viability and preventing senescence in Ewing sarcoma and permissive cells." (PMID 39367409, 2024). "In summary, we demonstrate that both EWS::FLI1 and EWS::ERG cooperate with P300 to maintain LMNB1 expression and evade senescence-related processes in Ewing sarcoma." (PMID 39367409, 2024).
glioblastoma (1 paper, 2020). The most malignant astrocytic tumor (WHO grade IV). "Western blotting of the levels of nuclear lamins showed a decrease in lamin B1 in both glioblastoma cell lines and lamin B2 in U251MG cells under arginine deprivation in combination with canavanine treatment." (PMID 33008000, 2020).
Gliosis (1 paper, 2025). Gliosis is the focal proliferation of glial cells in the central nervous system. "Notably, we observed reduced levels of Lamin B1 during gliosis, a protein commonly associated with cellular senescence." (PMID 40719049, 2025).
Globozoospermia (1 paper, 2024). Any structural anomaly of the acrosome resulting in a round sperm head. "An atypical nuclear membrane with abnormal nuclear pore distribution and lamin B1 localization was observed in spermatozoa from patients with both complete and partial globozoospermia." (PMID 39045326, 2024). "Staining with antibodies to lamin B1 was performed in semen samples from three individuals (patient 5 with complete globozoospermia, patient 12 with partial globozoospermia, and fertile normozoospermic man of the control group)." (PMID 39045326, 2024). "In semen samples with complete and partial globozoospermia, lamin B1 was observed at the periphery of sperm nuclei, whereas lamin A and progerin were absent." (PMID 39045326, 2024). "In patients with partial globozoospermia, localization of lamin B1 along the nuclear periphery was detected in 80% of sperm." (PMID 39045326, 2024). "In addition, we decided to test whether there was an abnormal distribution of lamin A in globozoospermia, similar to the distribution of lamin B. It is unknown whether lamin B1 localization is impaired in the sperm from patients with partial globozoospermia." (PMID 39045326, 2024). "We showed that lamin B1 is localized throughout the periphery of the nucleus, in contrast to sperm from fertile men, and found nuclear pores in the nuclear envelope of globular sperm outside the area of the nuclear pouches in patients with both forms of globozoospermia." (PMID 39045326, 2024). "Despite changes in the nuclear envelope and localization of lamin B1 in spermatozoa with globozoospermia, lamin A expression does not differ from that of spermatozoa with normal head morphology, which is consistent with previously published data." (PMID 39045326, 2024). "Abnormal nuclear envelope pore preservation and lamin B1 distribution have been found in spermatozoa from patients with complete and partial globozoospermia, regardless of the degree of chromatin condensation." (PMID 39045326, 2024).
Hyperglycemia (1 paper, 2025). An increased concentration of glucose in the blood. "This study demonstrated that Klotho overexpression significantly increased Lamin B1 levels, reduced p16, p21, and PAI-1 expression, and decreased the proportion of SA-β-Gal-positive cells in HK-2 cells exposed to AGE, underscoring Klotho’s protective role against senescence in hyperglycemia." (PMID 40823556, 2025).
inflammatory bowel disease (1 paper, 2022). A spectrum of small and large bowel inflammatory diseases of unknown etiology. "In inflammatory bowel disease (IBD), miR-23a and miR-155 enhance the deleterious effects of neutrophils by targeting lamin B1 and RAD51 (a homologous recombination regulator), inhibiting tissue healing responses." (PMID 35634335, 2022).
intracranial aneurysm (1 paper, 2025). "Moreover, the intracranial aneurysm tissue showed a lower expression of the aging marker Lamin B1 and a higher expression of the senescence marker P21." (PMID 41026146, 2025).
liver fibrosis (1 paper, 2022). "In summary, SIRT1 drives the nucleophagic degradation of progerin mediated by the deacetylation of nuclear LC3 and improves the depletion of Lamin B1 and Cav-1, leading to the maintenance of LSEC fenestrae and the relief of liver fibrosis." (PMID 36497176, 2022).
lymphoid tumours (1 paper, 2018). "In support of this hypothesis, we found a consistently decreased amount of Lamin B1 in the majority of primary lymphoid tumours, as compared with intrafollicular areas of normal human reactive lymph nodes." (PMID 28804121, 2018).
metastatic tumor (1 paper, 2020). "In addition, in skin cancer samples, lamin B1 RNA levels are higher in metastatic tumor samples than in primary tumor samples." (PMID 32987785, 2020).
Nephroblastoma (1 paper, 2016). An embryonal neoplasm characterized by the presence of epithelial, mesenchymal, and blastema components. "Mechanistically, down-regulation of Lamin B1 and up-regulation of Nephroblastoma overexpressed (NOV) were at least partially responsible for the inhibitory effect of Huaier on the proliferative and invasive capacity of SKHEP-1 cells." (PMID 27503760, 2016).
neuropathies (1 paper, 2014). "Moreover, mutations in several other NE components, such as lamin A, BAF, lamin B1, and the LINC complex (which connects the NE to the cytoskeleton), are associated with neuropathies affecting both the peripheral and central nervous system." (PMID 24490688, 2014).
ovarian serous cystadenocarcinoma (1 paper, 2022). A malignant serous cystic epithelial neoplasm arising from the ovary. "The total protein expression of lamin B1 was found significantly higher in the tumor tissues of all the six tumor kinds (BRCA, COAD, KIRC, LUAD, OV (Ovarian serous cystadenocarcinoma) and UCEC) whose normal tissue data were available in CPTAC, than the corresponding normal tissues." (PMID 35241075, 2022).
ovarian tumor (1 paper, 2025). "Notably, claudin-4 is known to be localized in the nucleus of ovarian tumor cells, where we observed an inverse relationship between claudin-4 expression and lamin B1 nuclear localization." (PMID 39625235, 2025).
primary biliary cholangitis (1 paper, 2020). Primary biliary cholangitis (PBC) is a chronic and slowly progressive cholestatic liver disease of autoimmune etiology characterized by injury of the intrahepatic bile ducts that may eventually lead to liver failure. "Our results suggest that hsa-miR-23b is involved in pathophysiology of primary biliary cholangitis through interleukin-12 signaling via regulation of CNN2, JAK1, LMNB1, MTAP, SOD2, and TCP1." (PMID 33036164, 2020).
proteinopathy (1 paper, 2024). "We assessed the lamin-B1-positive nuclear membrane structure was also disorganized in the remaining MNs, as observed in human TDP-43 proteinopathy." (PMID 39226364, 2024).
reactive lymphoid hyperplasia (1 paper, 2018). "To test whether the decrease in Lamin B1 was a general cross-species phenomenon related to GC formation, we next assessed a panel of tissue microarrays containing 42 human biopsies with previously diagnosed reactive lymphoid hyperplasia." (PMID 28804121, 2018).
retinal degeneration (1 paper, 2024). Degeneration of the retina. "To determine if SCA7 model mice display nuclear membrane pathology while undergoing retinal degeneration, we performed IHC on retinal sections from symptomatic SCA7 266Q knock-in mice and WT littermate controls by immunostaining for Lamin B1 and counterstaining with DAPI." (PMID 39649105, 2024).
Skin Cutaneous Melanoma (1 paper, 2022). "Besides, LMNB1 expression in the metastasis tissues of SKCM (Skin Cutaneous Melanoma) is much higher than the primary tumor tissues." (PMID 35241075, 2022).
small cell lung carcinoma (1 paper, 2018). Small cell lung cancer (SCLC) is a highly aggressive malignant neoplasm, accounting for 10-15% of lung cancer cases, characterized byrapid growth, and early metastasis. "In 1990s, Kaufmann and Broers’ teams showed that A-type lamins were expressed in non-small cell lung cancer (NSCLC) cell lines, but were absent or very weak in small cell lung cancer (SCLC) cell lines, with no variation of lamin B1 expression." (PMID 30012957, 2018).
Tremor (1 paper, 2019). An unintentional, oscillating to-and-fro muscle movement about a joint axis. "Unlike these diseases, LMNB1-related ADLD patients with tremor are extremely rare and ADLDs with tremor as the initial symptom have never been reported previously in China." (PMID 31695592, 2019).
uterine carcinosarcoma (1 paper, 2022). A usually aggressive malignant neoplasm arising from the uterine corpus and less often the cervix. "We found that all the TCGA cancers excluding UCS (Uterine Carcinosarcoma) showed statistical positive correlation between high LMNB1 expression and the immune infiltration of CD4+ Th2 cells based on XCELL algorithm." (PMID 35241075, 2022).
cancer (62 papers, 2007 to 2025). A tumor composed of atypical neoplastic, often pleomorphic cells that invade other tissues. "Human cancer cell types provide a spectrum between loss or maintenance of lamin B1 in the nuclear bleb relative to the body." (PMID 40060436, 2025). "In such cell types, lamin B1 can aid oxidative stress response, but at the cost of higher risk for radiosuspectibility for cancer." (PMID 39979866, 2025). "Human cancer cell types fall on a spectrum between loss and maintenance of lamin B1 in the nuclear bleb relative to the body." (PMID 41047936, 2025). "LMNB1 is also closely associated with the failure of normal cell cycle and the occurrence and development of various malignant tumors." (PMID 38824174, 2024). "The observed association is unlikely due to a mechanically induced lamin B1 upregulation considering that the cancer cells are fixed immediately after the deformation." (PMID 37218524, 2023). "This variability in lamin B1 expression and its association with clinical outcomes suggest that it has different contributions to cancer progression that appear to be cancer type specific." (PMID 35328162, 2022). "Proliferation is afterall a key hallmark of cancer but of course also occurs with stem and progenitor cells in mechanical microenvironments such as soft brain, where LMNB1 has also been noted as upregulated." (PMID 35719698, 2022). "Among these, artificial intelligence highlighted SLC27A4 and LMNB1 as proteins that maximize the discrimination between cancer and non-cancer samples, with SLC27A4 associated with controls, and LMNB1 with MB samples." (PMID 36005596, 2022). "In brief, we comprehensively analyzed the mRNA and protein levels of LMNB1, and its association with prognostic landscape across all TCGA cancer types." (PMID 35241075, 2022). "The impact of Progerin expression, decreased or increased Lamin A levels, or depletion of Lamin B1 on genome stability and on inflammation, another important hallmark of cancer, has started to emerge." (PMID 33918867, 2021). "Similar to previously characterized PMDs in somatic tissues and cancer samples, common fibroblasts PMDs described here overlapped with inactive, late-replicating, heterochromatic regions associated with H3K9me3 and Lamin-B1." (PMID 26182405, 2015). "We also found lamin B1 loss in irradiated cancer cell models A549 and MCF7 using immunoblotting." (PMID 41159617, 2025). "In cancers, lamin B1 expression are associated with promoting tumor aggressiveness." (PMID 40013266, 2025). "Additionally, 40/64 genes were linked to two or more cancers, with glycogen phosphorylase B (PYGB) and lamin B1 (LMNB1) having the most associations with seven cancer types." (PMID 39119785, 2024). "Recent studies have reported that LMNB1 was associated with cell senescence and multiple malignancies and may predict poor survival outcome of cancer patients." (PMID 38824174, 2024). "Increasing evidence indicates that LMNB1 is associated with tumor proliferation and metastasis in several types of human cancer, but as far as we know, there is little investigation focusing on the relationship between LMNB1 expression and immune cell infiltration." (PMID 35241075, 2022). "As we could demonstrate the deregulation of LMNB1 in MM, its influence on gene expression and, thus, its relevance in cancer-associated biological processes, we aimed to further investigate if these effects are also modulated by the lamin B receptor (LBR)." (PMID 35883595, 2022). "These functions and pathways are closely-associated cancer development, indicating that LMNB1 and LMNB2 could affect HCC progression through multiple cellular functions and signaling pathways." (PMID 36405011, 2022). "Moreover, a positive association between lamin B1 levels and tumor formation and progression is found in various cancer types." (PMID 32987785, 2020).